ERBB2 (erb-b2 receptor tyrosine kinase 2)
Diseases named in the same sentence as ERBB2 in open-access papers (continued):
Sharing a sentence is not in itself a finding about the gene and the disease.
prostate carcinoma (375 papers, 2001 to 2026). A carcinoma that arises from epithelial cells of the prostate gland. "For example, HSP90 interfaces with different key proteins in inducing prostate cancer progression, comprised both wild-type and mutated AR, HER2, ErbB2, Src, Abl, Raf, and Akt." (PMID 36675080, 2023). "To overexpress ERBB2 and RAS oncogenes in prostate cancer cell lines, we transfected prostate cancer cells with pBabe-Puromycin- (PBP-) based retroviruses overexpressing an activated form of ERBB2 (PBP-ERBB2) or a mutated form of H-RAS (PBP-RAS)." (PMID 24937171, 2014). "It was reported that overexpression of ERBB2 activated AR pathway in prostate cancer cells in an androgen-deficient milieu." (PMID 24739220, 2014). "Interestingly, ERBB2 overexpression has been implicated in androgen-resistant metastatic prostate cancers, suggesting a possible role for ERBB2 in the acquisition of metastatic potentials of prostate cancer cells." (PMID 24937171, 2014). "In addition, overexpression of ErbB-2 and ErbB-3 has been implicated in the neoplastic transformation of prostate cancer." (PMID 22606295, 2012). "Other prostate cancer-associated somatic mutations were consistent in some PDOs and parental tumours, such as BRCA1, ALK, STED2, TET2, TRPM8, AURKA, ERBB2, GATA2." (PMID 41403018, 2025). "ERBB2 recruitment enhances PI3K/AKT signaling in prostate cancer cells, serving as a key mediator of EGF-induced proliferation." (PMID 41331197, 2025). "ITGB4 has also been shown to play a crucial role in the development of prostate cancer found that ITGB4 promotes prostate tumorigenesis by co-expression with ErbB2 and c-Met in tumor progenitor cells." (PMID 38172503, 2024). "miR-331-3p has been proven to be a promoting tumor regulator in prostate cancer, which acts as a mediator of ErbB-2 expression and PI3K/AKT signaling." (PMID 39512836, 2024). "For example, ERBB2 alterations co-segregate strongly with BRCA1 and are known to be associated with tumor aggressiveness in primary prostate cancer, tumor progression and invasion in advanced prostate cancer, and shorter time to castration-resistance." (PMID 36185208, 2022). "A recent study revealed that the combined protein expression patterns of EGFR, ERBB2, and ERBB3 were associated with a higher risk of progression and mortality in prostate cancer." (PMID 36095024, 2022). "Concomitant amplification or copy number gain of two genes is a common phenomenon in cancers, such as MYCN and DDX1 in neuroblastoma, ERBB2/HER2 and TOPOIIα in prostate cancer." (PMID 34461927, 2021). "miR-331-3p has been proven to be a tumor regulator in prostate cancer, which acts as a mediator of ErbB-2 expression and PI3K/AKT signaling." (PMID 32596340, 2020). "For instance, PREDICT uses ERBB2 (formerly HER2 or HER2/neu) status, estrogen receptor status, and tumor size; the prostate cancer nomograms require knowledge of prostate-specific antigen levels, biopsy cores, or pathology reports." (PMID 32236529, 2020). "Our analyses on primary tumor showed that CNV in different exons of ERBB2 were associated with aggressive UCB features, e.g. presence of variant histology, pathologic tumor stage, LVI and MVI, and incidental prostate cancer." (PMID 33298978, 2020). "In serum, CNV in CCND1 was associated with MVI (p = 0.004); CNV in PTP4A, KRAS, ERBB2, TOP2A with positive STSM (p ≤ 0.035); CNV in CCND1 with the presence of incidental prostate cancer (p = 0.018)." (PMID 33298978, 2020). "Apart from that, the role of EGFR/Erb-B2 receptor tyrosine kinase 2 (ERBB2) signaling in prostate cancer metastasis into the bone microenvironment has also been enumerated." (PMID 31137764, 2019). "The overexpression of the epidermal growth factor receptor (EGFR) and the protein, v-erb-b2 erythroblastic leukemia viral oncogene homolog 2 (ErbB2), have been reported to be involved in cancer progression and development, including prostate cancer." (PMID 31126091, 2019).
prostate carcinoma (continued). "AR controls EGFR and ErbB2 expression in prostate cancer cells and in turn EGFR and ErbB2 concur to PCa progression activating AR signaling in hormone-poor conditions." (PMID 31816863, 2019). "MiR-331-3p has been shown to suppress ERBB2 signaling in prostate cancer while ERBB-2 was indicated to be correlated with chemoradiation therapy resistance in muscle invasive bladder cancer patients." (PMID 29599914, 2018). "In our previous study, we demonstrated that rs61552325 (Pro1140Ala) located in ERBB2 is strongly correlated to prostate cancer." (PMID 28422721, 2017). "The accumulation of ERBB-2 in prostate cancer cells leads to the activation of signalling pathways, such as the phosphatidylinositol-3-kinase (PI3K)/AKT signalling pathway, which correlates with cancer progression and therapy resistance." (PMID 26404389, 2015). "In prostate cancer cells, HuR was shown to compete with miR-331-3p for regulation of erb-B2 receptor tyrosine kinase 2 (ERBB2) mRNA." (PMID 26512708, 2015). "Previous work showed that ErbB2 inhibition improved the cytoxic effect of gemcitabine in prostate cancer cells." (PMID 25890497, 2015). "In the present study, we have shown that overexpression of H-RAS and overexpression of ERBB2 had different impacts on the metastatic potentials of various prostate cancer cell lines." (PMID 24937171, 2014). "We and others identified several targets of miR-331-3p in prostate cancer cells, including ErbB-2, DOHH and KLK4." (PMID 24142150, 2014). "Given that miR-331-3p represses ERBB2 expression and signal transduction in prostate cancer cells it seems reasonable to note that ERBB2 targeting destabilizes AR." (PMID 24739220, 2014). "This microRNA is able to reduce v-erb-b2 avian erythroblastic leukemia viral oncogene homolog 2 (ERBB2) expression, a known oncogene whose expression increases in advanced prostate cancer, and to impair AR signaling pathway." (PMID 25309903, 2014). "One of the best studied genes in human malignancies, including prostate cancer, is the ERBB2 or HER2 or NEU oncogene." (PMID 24937171, 2014). "As one of the critical downstream effectors of ERBB2 pathway, RAS oncogene has been previously implicated in prostate cancer metastasis." (PMID 24937171, 2014). "EGFR belongs to ErbB oncogene family which also includes ErbB-2, 3, and 4 and is comprehensively expressed in epithelial cells including prostate cancer cells." (PMID 24741584, 2014). "ErbB2 is a member of the epidermal growth factor family of tyrosine kinases that is centrally involved in the pathogenesis of prostate cancer and several studies have reported that a high expression of this protein has prognostic value." (PMID 25215939, 2014). "ERBB2 overexpression led to moderate increases in growth rates for all of the three human prostate cancer cell lines: an average of 43% increase for LnCaP cells, 33% increase for DU145 cells, and 25% increase for PC3 cells." (PMID 24937171, 2014). "To do so, we first transfected three commonly used human prostate cancer cell lines (DU145, LnCaP, and PC3) and one murine prostate cancer cell line (Myc-CaP) with the activated form of ERBB2 or H-RAS." (PMID 24937171, 2014). "The metastatic potentials of ERBB2- or RAS-overexpression in various prostate cancer cell lines were further assessed by evaluating their relative invasiveness by a transwell-based invasion assay using cell inserts coated with a collagen matrix." (PMID 24937171, 2014). "Recent studies have suggested that EGFR or ERBB2 contribute to prostate cancer (PCa) progression by activating the androgen receptor (AR) under hormone-poor conditions." (PMID 24223781, 2013). "Recent advances demonstrate that cellular PAcP (cPAcP) functions as a protein tyrosine phosphatase by dephosphorylating ErbB-2/Neu/HER-2 at the phosphotyrosine residues in prostate cancer (PCa) cells, which results in reduced tumorigenicity." (PMID 23698773, 2013).
prostate carcinoma (continued). "Supportively, ERK1/2 are activated in advanced prostate carcinomas and AI PCa cells in which cPAcP is decreased or null, suggesting that decreased cPAcP results in activated ErbB-2 and down-stream ERK1/2 signaling for CR PCa progression." (PMID 23698773, 2013). "ErbB-related pathways were identified in the metastatic network, including the ErbB network pathway, ErbB4 pathway, Her2 pathway, ErbB2/ErbB3 signaling pathway and the EGFR pathway, which are implicated in prostate cancer progression and metastasis." (PMID 23782521, 2013). "Although the exact role of these oncogenes and growth factors in prostate carcinoma is still unclear, overexpression of ErbB-1 and ErbB-2 has been related to poor prognosis and distant metastasis." (PMID 22606295, 2012). "The LNCaP androgen-dependent cell line expresses high levels of ErbB-2 and ErbB-3 compared to other human prostate cancer cells." (PMID 22606295, 2012). "The androgen dependent prostate cancer cell line, LNCaP, expresses the ErbB-1, ErbB-2 and ErbB-3 receptor tyrosine kinases." (PMID 22606295, 2012). "Activated ERK mediates activation of the androgen receptor and/or PSA secretion through the growth factor receptor tyrosine kinase, Her2/Neu (also known as erbB2) in androgen-independent prostate cancer cells." (PMID 22046506, 2012). "For example, HSP90 interacts with several key proteins in promoting prostate cancer progression, including wild-type and mutated AR, HER2, ErbB2, Src, Abl, Raf and Akt." (PMID 21345215, 2011). "Amplification of members of the MAPK pathway was associated with androgen independent prostate cancer, and co-expression of RAF1, ERBB2/HER2 and c-FOS would lead to this phenotype." (PMID 20805891, 2010). "ERBB2 has been shown to stabilize AR protein in prostate cancer cells and to activate the Akt pathway." (PMID 20712882, 2010). "Intriguingly, the RNA expression of ERBB2 was observed at levels similar to the highly expressed TROP2 and PSMA, suggesting that posttranscriptional factors may have an influence on the low level of HER2 expression observed in prostate cancer." (PMID 40767528, 2025). "ACP3 is a prostatic acid phosphatase that also regulates prostate cancer cell growth by dephosphorylating ERBB2, which is a part of the adjacent network of our target gene CHST2 in our previous study that shows a slight negative correlation with TPS and deactivates MAPK-mediated signalling." (PMID 39457550, 2024). "In addition, prostate cancer had a high rate of therapeutic target mutations, including BRCA1/2, CDK12 mutations, and ERBB2 amplification." (PMID 36251535, 2023). "This hypothesis is consistent with our in vitro findings: knockdown of Plexin-B1 reduces migration and invasion in prostate cancer cells expressing ErbB2, while activation of endogenous Plexin-B1 with Sema4D promotes migration and invasion." (PMID 36936664, 2023). "A loss of hsa-mir-331-3p expression could promote the increased ERBB-2 expression and signaling seen in many prostate cancers." (PMID 36291575, 2022). "Studies have suggested a role for EGFR and ERBB3 in the development of prostate cancer (PC), while the involvement of ERBB2 and ERBB4 remains unclear." (PMID 33918389, 2021). "The study suggested that osteoblast-directed induction of signaling activity involving EGFR and ERBB2 in prostate carcinoma cells might be culpable in bone metastasis." (PMID 31137764, 2019). "Furthermore, β4-integrin was found to amplify ErbB2 and c-Met signaling pathways to promote prostate carcinoma cell proliferation and invasion." (PMID 30782177, 2019). "Considering that activation of the ERBB2/RAS signaling pathway in prostate cancer cells may affect their growth rates, which could influence the analysis to assess their metastatic potentials, we carried out a growth curve assay using asynchronous cells." (PMID 24937171, 2014).
prostate carcinoma (continued). "In vitro functional studies revealed that Cathepsin B could be secreted into extracellular compartments and that Cathepsin B mediated the effects of ErbB2 and S1p in breast and prostate cancer cell invasion." (PMID 24705283, 2014). "In addition the v-erb-b2 erythroblastic leukemia viral oncogene homolog 2, neuro/glioblastoma derived oncogene homolog (avian) (ERBB2) is another important receptor that is dysregulated in prostate cancer." (PMID 24739220, 2014). "A detailed mechanistic investigation indicated that specific binding of the RNA binding protein- ELAV (embryonic lethal, abnormal vision, Drosophila)-like 1 (Hu antigen R) (HuR; ELAVL1) to this U-rich element momentously enhanced ERBB2 expression in prostate cancer cells." (PMID 24739220, 2014). "It would be interesting to know whether the ability of ERBB2 to increase prostate cancer metastatic potentials depends on the activation of the p38 kinase signaling pathway and the down-regulation of the ERK signaling pathway." (PMID 24937171, 2014). "Therefore, our data does not rule out the possibility that the relatively high metastatic property of the PC3 cells and DU145 cells contributes to the ability of ERBB2 to promote prostate cancer metastasis in those cells." (PMID 24937171, 2014). "It is concluded that tumour ErbB2-IR is of limited clinical value as a prognostic marker to aid treatment decisions, but could be of pathophysiological importance in prostate cancer." (PMID 25215939, 2014). "To evaluate and define the role of the ERBB2/RAS pathway in prostate cancer metastasis, we have evaluated the impact of ERBB2- or RAS-overexpression on the metastatic potentials for four prostate cancer cell lines derived from tumors with different androgen sensitivities." (PMID 24937171, 2014). "The importance of ErbB2 in the pathogenesis of prostate cancer (Pca) is less clear." (PMID 25215939, 2014). "ErbB2 is frequently overexpressed in breast, gastric, ovarian and prostate cancer." (PMID 25016581, 2014). "Moreover, ErbB-2 overexpression is a common event that appears to confer a selective advantage to several types of carcinomas including prostate cancer." (PMID 22606295, 2012). "However, studies of the role of ErbB2 in clinical prostate cancer remain inconclusive, and initial clinical trials indicate that the anti-ErbB2 antibody Herceptin (trastuzumab) does not show significant clinical activity as a single agent." (PMID 15583694, 2005). "The cytoplasmic staining of p185c-erbB-2 has already been reported in prostate cancers." (PMID 12942124, 2003). "The physiologic significance of ErbB2 in CRPC is supported by studies showing increased ErbB2 expression or activity in CRPC clinical samples, although this is not a consistent finding, and increased ErbB2 has also been associated with more aggressive primary untreated prostate cancer." (PMID 35645241, 2022). "ErbB-2 signal transduction upregulates the activity of ST14, which in turn promotes the invasion of prostate cancer cells." (PMID 38468232, 2024). "In prostate cancer, CAF-derived NRG1 can promote resistance to anti-androgen therapy by stimulating ERBB2/ERBB3 heterodimers in cancer cells." (PMID 36357571, 2023). "The most prominently involved pathways for the upregulated proteins were the viral process and ERBB2 signaling (GO) and EGFR tyrosine kinase inhibitor resistance as well as prostate cancer (KEGG)." (PMID 31323891, 2019). "In prostate cancer cell lines, resveratrol reduced the levels of several receptor tyrosin kineses (EGFR, ErbB2/HER2, IGFR-1) in a time-dependent manner, particularly in androgen-negative prostate cancer cells." (PMID 30823649, 2019). "Here, we show that SEMA3C is a secreted soluble autocrine growth factor that drives growth and treatment resistance of prostate cancer via activation of multiple RTKs such as EGFR, MET, and ErbB2 in a cognate ligand‐independent manner." (PMID 29348142, 2018).
prostate carcinoma (continued). "Our results showed that these genes are involved in multiple pathways of cancer, prostate cancer, focal adhesion, lipid metabolism, constitutive PI3K/AKT signaling, EGFR, PDGF, FGFR, ERBB2/DAP12 and MAPK signaling pathways." (PMID 30397274, 2018). "In summary, this study identifies SEMA3C as a key secreted, autocrine growth factor that drives PCa growth and castration‐ and treatment‐resistant prostate cancer progression through activation of EGFR, HER2/ErbB2, MET, and c‐SRC tyrosine kinase pathways." (PMID 29348142, 2018). "The effects of ERBB2 and RAS overexpression on the metastatic potentials of LnCaP, DU145, PC3, and Myc-CaP prostate cancer cell lines were first assessed by performing a wound healing assay." (PMID 24937171, 2014). "Overexpression of ERBB2 and RAS showed various effects on the three human prostate cancer cell lines." (PMID 24937171, 2014). "To complement the wound healing data presented above, we also assessed the effects of overexpression of ERBB2 and RAS on the cell motility of the prostate cancer cell lines by a transwell-based cell motility assay using porous membrane inserts in transwells." (PMID 24937171, 2014). "ERBB2 and ERBB3 considerably increase the androgen-dependent AR transactivation of reporter genes in prostate cancer cells." (PMID 24739220, 2014). "Using a similar approach we previously identified ErbB-2 and Deoxyhypusine hydroxylase (DOHH) as novel targets of miR-331-3p in prostate cancer." (PMID 24142150, 2014). "In prostate cancer, accumulating evidence has indicated that EGFR/ERBB2 signals induce AR transactivation in an androgen-dependent and -independent manner." (PMID 22922989, 2012). "Specifically, in prostate cancer cells, AR signals upregulate EGFR and ERBB2 gene expression, whereas activation of EGFR and ERBB2 modulates AR functions." (PMID 22922989, 2012). "This family of proteins has been extensively studied in breast, lung, colon and prostate cancer and its members include EGFR/ErbB1, Her-2/ErbB2, Her-3/ErbB3 and Her-4/ErbB4." (PMID 24281100, 2010). "ErbB2/HER-2 is another tyrosine kinase overexpressed in approximately 20–30% of breast and prostate cancers." (PMID 19401686, 2009). "In prostate cancer, ACPP functions as a tumor suppressor by dephosphorylating ERBB2." (PMID 40839607, 2025). "Re-expression of CAMK2N1 in prostate cancer cells reduced cellular proliferation, arrested cells in G0/G1 phases, and induced apoptotic cell death accompanied by down-regulation of IGF-1, ErbB2, and VEGF downstream kinases PI3K/AKT, as well as the MEK/ERK-mediated signaling pathways." (PMID 25003983, 2014). "In contrast, ERBB2 overexpression significantly reduced the motilities of the two lowly or non-metastatic, androgen-sensitive prostate cancer cell lines, LnCaP and Myc-CaP." (PMID 24937171, 2014). "Truncated androgen receptors in prostate cancer 22Rv1 cells can bind DNA in the absence of ligand and repress the ERBB2 gene repression and for the 22Rv1 cell castration resistant phenotype." (PMID 24739220, 2014). "Specifically, while overexpression of ERBB2 had no significant impact on the migration rates of all of the three human prostate cancer cell lines, overexpression of RAS significantly decreased the migration rates of LnCaP and DU145 cell lines." (PMID 24937171, 2014). "Therefore, it is understandable that miRNA mediated control of AR is lost in TMPRSS2-ERG positive prostate cancer and ELAVL1 stabilizes the expression of AR and ERBB2 which synchronously trigger the expression of cancer promoting genes." (PMID 24739220, 2014). "Whereas trastuzumab has recently been approved for the treatment of metastatic gastric cancer in combination with cytotoxic agents, similar studies targeting overexpressed/amplified ERBB2 in NSCLC and prostate cancer have reported modest or disappointing results." (PMID 23630663, 2013).